ANXA1 (annexin A1)
Diseases named in the same sentence as ANXA1 in open-access papers (continued):
Sharing a sentence is not in itself a finding about the gene and the disease.
colorectal cancer (34 papers, 2012 to 2025). A primary or metastatic malignant neoplasm that affects the colon or rectum. "By constructing a risk model, Liang and Li (2021) found that ANXA1 expression levels were associated with the level of immune infiltration in colorectal cancer." (PMID 36936694, 2023). "Our data showed that ANXA1 gene and protein were down-regulated in all GI cancers, and was associated with high pathological grade, larger tumor size, and advanced stage in colorectal carcinoma." (PMID 29091952, 2017). "Interestingly, in the colorectal cancer cohort, the probability of survival trended towards higher ANXA1 expression being associated with a survival advantage versus those in the lower quartile of expression, although this was not statistically significant." (PMID 38200229, 2024). "Additionally, the current results revealed that miR-196a2, ANXA1, and annexin A1 deregulation were associated with unfavorable prognosis in colorectal carcinoma patients." (PMID 29091952, 2017). "ANXA1 expression in tumors was found to be tissue-specific, as evidenced by increased levels in lung, liver, and colorectal cancers, while it showed decreased levels in prostate, nasopharyngeal, and oral squamous cell carcinomas." (PMID 40158127, 2025). "MDX-124 caused a significant reduction in cellular proliferation in all breast, pancreatic, ovarian and colorectal cancer cell lines expressing ANXA1 when compared to an IgG1 isotype control antibody (p < 0.05)." (PMID 38200229, 2024). "In colorectal cancer, ANXA1 (Annexin A1), has been shown to be associated with a worse prognosis and an increased immune cell infiltrate." (PMID 37386001, 2023). "The elevation of ANXA1 has been detected in colorectal cancer patients with micro-metastases in the anterior lymph nodes than in matched individuals with normal lymph nodes." (PMID 36936694, 2023). "Bioinformatics-aided analysis of annexin A1 gene expression identified three studies where this molecule was significantly overexpressed in colorectal cancer samples compared with normal colonic mucosa." (PMID 31545917, 2019). "Our results point to annexin A1 as a putative biomarker or therapeutic target in liver metastases from colorectal cancer." (PMID 31545917, 2019). "Strong to moderate positive correlation was observed between PDCD4 and DFFA in esophageal cancer tissues (r = 0.657, P = 0.039), and between PDCD4 and ANXA1 in gastric carcinoma (r = 0.683, P = 0.007) and colorectal cancer (r = 0.617, P = 0.001)." (PMID 29091952, 2017). "In colorectal cancer, over-expression levels of miR-196a were negatively correlated with annexin A1 protein expression (r = -0.738, P < 0.001)." (PMID 29091952, 2017). "Stratified analysis by cancer site revealed that miR-196a2, ANXA1 gene, and annexin A1 protein were indicators of poor prognosis in colorectal cancer." (PMID 29091952, 2017). "Moreover, the adhesin FadA of F. nucleatum promotes colorectal cancer oncogenesis through the expression of annexin 1 (ANXA1) and Cyclin D1." (PMID 41296437, 2025). "Moreover, in colorectal cancer samples, high ANXA1 expression promoting macrophage polarization towards an M2-like phenotype is associated with immunosuppression and strongly correlated with poor prognosis." (PMID 39428941, 2025). "ANXA1 could therefore be used as a biomarker for colorectal cancer diagnoses and as an independent prognostic indicator for patients." (PMID 36936694, 2023). "Expression of annexin A1 in colorectal cancer liver metastases." (PMID 31545917, 2019). "With the use of this unbiased method, we further examined annexin A1 as a putative therapeutic target for colorectal cancer by comprehensively characterizing its expression levels, tissue localization, cellular source in the tumor microenvironment (TME), and potential role in the ECM milieu." (PMID 31545917, 2019). "Taken together, these data indicate that annexin A1 is frequently expressed in colorectal cancer ECM and may be important for progression of this disease." (PMID 31545917, 2019).
colorectal cancer (continued). "Additionally, up-regulated ANXA1 promoted tumour invasion and metastasis as seen in colorectal cancer whereby ANXA1 levels were raised in sentinel lymph nodes compared to normal lymph nodes." (PMID 29614751, 2018). "In colorectal cancer, miR-196a over-expression was negatively correlated with annexin A1 protein expression (r = -0.738, p < 0.001), and both were indicators of unfavorable prognosis in terms of poor differentiation, larger tumor size, and advanced clinical stage." (PMID 29091952, 2017). "Interestingly, it has also been shown that the translocation of ANXA1 to the cell surface is partially responsible for promoting cell migration and invasion in colorectal carcinoma cell line SKCO-15, indicating an autocrine/paracrine role for membrane ANXA1." (PMID 25510623, 2014). "Additionally, recent studies have indicated that secreted ANXA1 in plasma may function as a circulating biomarker for the diagnosis of COVID-19 and colorectal cancer, thus suggesting its prospective roles in the diagnosis of PDAC." (PMID 40484878, 2025). "Finally, we questioned whether altered annexin A1 expression may influence prognosis of patients with colorectal cancer." (PMID 31545917, 2019). "It is worth noting that the upregulation of annexin A1 is associated with increased levels of carcinoembryonic antigen (CEA), which is only produced in gastrointestinal tissue during fetal development and is one of the most commonly used markers in colorectal cancer." (PMID 28423508, 2017). "The effect of punicalagin on the expression of Annexin A1 (Anx‐A1) and the interplay between apoptosis and autophagy in HCT 116 colorectal cancer cells was studied by researchers in a recent study." (PMID 40018013, 2025). "Silencing of ANXA1 has been reported to reduce tumour growth in vivo in other studies where ANXA1 knockdown in SUM149 TNBC and HCT116 colorectal cancer cells grown as subcutaneous xenografts have been shown to grow significantly slower than non-silenced cancer cells." (PMID 38200229, 2024). "Annexin A1 is little studied in the context of colorectal cancer, and its ECM localization is not recognized." (PMID 31545917, 2019).
gastric cancer (32 papers, 2007 to 2026). A primary or metastatic malignant neoplasm involving the stomach. "In gastric cancer, the nuclear expression of AnxA1 is associated with advanced stages of the disease and with peritoneal dissemination." (PMID 34571894, 2021). "Immunohistochemistry data obtained with tissue microarrays reported loss of ANXA1 in 64% of primary gastric cancers and 86% of lymph node metastases, arguing for a tumor-suppressive function of ANXA1 in gastric cancer." (PMID 26760764, 2016). "In present study, however, we observed a significant loss of ANXA1 expression in cholangiocarcinoma and gastric cancer." (PMID 25038797, 2014). "In the present study, we evaluated AnxA1 and Gal-1 anti-inflammatory proteins and mRNA expression in a group of precursor lesions such as chronic gastritis compared to gastric cancer and their association with risk factors." (PMID 23431236, 2013). "Additionally, AnxA1 expression was certainly associated with invasiveness of human gastric cancer cells both in vitro and in vivo studies." (PMID 29867026, 2018). "Gain/loss-of-function by pcDNA3.1-ANXA1 and ANXA1-shRNA was performed in gastric cancer cells." (PMID 25038797, 2014). "Gastric cancer patients with high AnxA1 expression in tumors had worse overall survival compared with patients with low or no AnxA1 expression in tumors." (PMID 36766501, 2023). "ANXA1 and ANXA2 were selected, since they are described to play a role in gastric cancer and ANXA2 was found to be up-regulated in H. pylori-associated gastric cancer." (PMID 35176125, 2022). "In line with our observation, ANXA1 mRNA and protein expressions were markers of differentiation in squamous cell carcinoma of the cervix, head and neck, esophageal and gastric cancer." (PMID 29091952, 2017). "Contradictory expression pattern and clinical relevance of ANXA1 have been reported in human gastric cancer." (PMID 28600569, 2017). "In order to investigate the functional role of ANXA1 in GC progression and metastasis, we assessed the impact of ANXA1 knockdown and over expression on gastric cancer cell migration and invasion." (PMID 27941907, 2016). "Our data demonstrated that ANXA1 is indeed over–expressed in gastric cancer, but expressed at low levels in normal gastric tissue." (PMID 27941907, 2016). "Studies based on cDNA microarray analyses reported differentiation-dependent expression of ANXA1 in human gastric cancer with higher expression in diffuse-type than in intestinal-type gastric cancers." (PMID 26760764, 2016). "Recently, we showed a similarly increased expression of annexin-A1 and galectin-1 in chronic gastritis and in gastric cancer, evidencing deregulation in the expression of these proteins during the initial step of gastric carcinogenesis." (PMID 24719523, 2014). "In this context, we found that overexpression of ANXA1 aborgated COX-2 expression in gastric cancer cells." (PMID 25038797, 2014). "Studies on annexin-A1 and galectin-1 in gastric cancer and precancerous lesions are few and reveal contradictory results." (PMID 24719523, 2014). "Forced ANXA1 expression in gastric cancer cells leads to cell growth inhibition and concomitantly modulates COX-2 expression." (PMID 25038797, 2014). "To confirm our findings, we investigated ANXA1 expression in a cohort of 52 gastric cancer cases and compared the results with expression in surrounding benign tissue." (PMID 25038797, 2014). "Immunohistochemistry for ANXA1 in cholangiocarcinoma and gastric carcinoma displayed positively staining cells mainly localized in well-differentiated carcinomas and rarely in poorly differentiated carcinomas." (PMID 25038797, 2014). "Five of these cases showed a decreased expression of ANXA1 in gastric carcinomas compared with surrounding normal gastric tissue, while the other three showed an increased expression of ANXA1." (PMID 25038797, 2014). "Similar to cholangiocarcinoma, in gastric carcinomas, ANXA1 mRNA was slightly down-regulated 1.2-fold." (PMID 25038797, 2014).
gastric cancer (continued). "The authors also proposed a new mechanism of how AnxA1 regulates the gastric cancer cell invasion through activation FPR/ERK/ITGB1BP1 pathway." (PMID 23431236, 2013). "In some areas of gastric cancer samples, it was possible to identify epithelial cells showing AnxA1 and Gal-1 expression." (PMID 23431236, 2013). "In conclusion, CTHRC1 expression may induce tumor associated macrophage infiltration though GRN/TNFRSF1A and AnxA1/FPR1 pathways and also tumor angiogenesis in gastric cancer." (PMID 35928443, 2022). "However, ANXA1 promotes tumor development by inducing cell migration and invasion with formyl peptide receptors in colon and gastric cancers." (PMID 33959206, 2021). "In gastric cancer, AnxA1 up-regulation correlates with advanced stages of the disease and peritoneal dissemination, while, in nasopharyngeal cancer, AnxA1 has also been described for promoting migration, invasion and metastasis formation, by mediating autophagy suppression." (PMID 34571894, 2021). "Deregulation of ANXA1 was found in both precancerous gastric lesions and gastric cancer." (PMID 25983750, 2015). "However, ANXA1 protein expression was almost completely lost in a number of gastric cancer specimens (D and 2 forth panel)." (PMID 25038797, 2014). "We confirm loss of ANXA1 and overexpression of COX-2 in clinical gastric cancer, suggesting that the anti-proliferative function of ANXA1 against COX-2 production might be lost." (PMID 25038797, 2014). "Furthermore, we examined COX-2 expression in these gastric cancer cases and investigated their correlation with ANXA1 expression." (PMID 25038797, 2014). "Using tissue microarray analysis, we previously demonstrated a significant loss of ANXA1 expression in human primary gastric cancer compared with that in adjacent non-neoplastic mucosa." (PMID 25038797, 2014). "Concerning the exact physiological functions of nuclear-translocated ANXA1 protein, accumulated evidence like in oral squamous cell carcinoma, gastric carcinoma and oesophageal squamous cell carcinoma, indicate that ANXA1 nuclear expression correlates with advanced disease and cancer dissemination." (PMID 25510623, 2014). "It has also been proposed that ANXA1 expression may correlate with the tumorigenesis, of thyroid and gastric cancer, which emphasizes the importance of ANXA1 in different kinds of cancers." (PMID 23119007, 2012). "In addition, CTHRC1 expression may induce tumor associated macrophage infiltration though GRN/TNFRSF1A and AnxA1/FPR1 pathways and also tumor angiogenesis in gastric cancer." (PMID 35928443, 2022). "Furthermore, we found an overexpression of MMP-9, that promotes tumor invasion and is associated with poor prognosis in gastric cancer, ANXA1 and ANXA4, overexpressed in gastric cancer and associated with proliferation, AREG, that promotes malignant progression in several types of cancer." (PMID 34012923, 2021). "However, other studies suggest ANXA1 expression during the early stages of gastric cancer." (PMID 32099594, 2019). "The increase of annexin-A1 expression in the lesions analyzed indicates a possible involvement in the progression of gastric carcinogenesis from early lesions, as observed in our previous study in chronic gastritis and now in intestinal metaplasia and gastric ulcer, to gastric cancer." (PMID 24719523, 2014). "By upregulation of ANXA1 with plasmid containing full-length ANXA1, we could significantly inhibit the anchorage-independent cell growth of gastric cancer cells, further supporting the importance of ANXA1 in the progression of gastric cancer." (PMID 25038797, 2014). "In conclusion, our study revealed the role of ANXA1, NNMT, Fibulin-5 and UQCRC1 in gastric cancer progression." (PMID 27941907, 2016). "Taken together, the comparative analysis of HIF-1α, ANXA1 and MYC expression in human gastric cancer samples confirmed the in vitro data, further indicating a potential functional association between HIF-1α, ANXA1 and MYC in this tumor entity." (PMID 26760764, 2016).
gastric cancer (continued). "YC and DX participated the immunohistochemistry analysis of ANXA1 and COX-2 in gastric cancer patients and assisted the analysis of data." (PMID 25038797, 2014). "We could show that simultaneous inhibition of HIF-1α and ANXA1 leads to robust and non compensable cell death, arguing for a combination therapy of HIF-1 and ANXA1 inhibitors for gastric cancer." (PMID 26760764, 2016). "To investigate the potential interaction between HIF-1α, ANXA1 and MYC in primary gastric cancer, we performed a bioinformatics analysis of co-occurrence and mutual exclusivity using a RNA-seq data-set from the TCGA data-base with 265 samples of stomach adenocarcinoma (cBioPortal)." (PMID 26760764, 2016). "Interestingly, 80.4% of HIF-1α-positive gastric cancers were negative for ANXA1, further supporting the notion of mutual exclusivity." (PMID 26760764, 2016). "Therefore, the aim of this study was to investigate the relative expression levels of ANXA1 and LGALS1 mRNA by quantitative real-time PCR (qPCR) and the expression of both proteins by immunohistochemical assay in inflammatory gastric lesions such as chronic gastritis compared to gastric cancer." (PMID 23431236, 2013).
Stroke (29 papers, 2012 to 2025). Sudden impairment of blood flow to a part of the brain due to occlusion or rupture of an artery to the brain. "Secreted ANXA1 interacts with FPRs and is involved in inflammation, neuroendocrine system regulation, skeletal muscle differentiation and cancer progression, while nuclear translocation of ANXA1 is implicated in neuronal apoptosis after stroke." (PMID 30364320, 2018). "A protective role for ANXA1 in various pathological conditions that are implicated with augmented platelet activation has been reported previously, e.g., atherosclerosis, myocardial infarctions, and strokes." (PMID 36834844, 2023). "However, the anti-thrombotic effect of AnxA1 in patients with co-morbidities susceptible to stroke is less well characterized." (PMID 33202930, 2020). "Both murine and human stroke are associated with decreased circulating levels of AnxA1, which may help to explain the exacerbated thromboinflammatory response seen in stroke." (PMID 31154815, 2019). "Therefore, the critical factors and mechanisms underlying ANXA1 nuclear translocation after stroke are being urgently sought." (PMID 29844306, 2018). "Thus, AnxA1 could be used as a viable treatment therapy in stroke to protect against I/RI by reducing the associated thromboinflammation." (PMID 31154815, 2019). "Interestingly, human and murine stroke is associated with decreased circulating levels of AnxA1." (PMID 31154815, 2019). "The restoration of plasma ANXA1 levels after stroke is indicative of a favorable recovery in stroke patients, suggesting its potential as a biomarker and valuable prognostic tool." (PMID 39475881, 2024). "Overall, CH preconditioning’s neuroprotective actions against cerebral ischemia are attributed to ANXA1 upregulation, suggesting a promising therapeutic avenue for stroke treatment." (PMID 38639785, 2024). "Similar observations were noted in a previous study that analysed the significance of ANXA1 in the regulation of post-thrombotic events following a stroke." (PMID 36834844, 2023). "In fact, ANXA1 administration significantly decreases both platelet adherence to the inflamed cerebral endothelium after stroke and regulates the state of platelet activation." (PMID 33804219, 2021). "Correspondingly, whole protein AnxA1 has also been shown to afford protection against subsequent thrombotic events post stroke, demonstrating the diversity of AnxA1 and its mimetic peptide." (PMID 33202930, 2020). "Specifically, AnxA1 administration reduced both platelet adherence to the inflamed cerebral endothelium after stroke and regulated the state of platelet activation." (PMID 31154815, 2019). "These experiments showed that selective antagonism of neutrophil Fpr2/ALX prevented the ability of AnxA1 to reduce PNA recruitment to the cerebral endothelium after stroke." (PMID 31154815, 2019). "The neuroprotective role of ANXA1 was also demonstrated in a rat stroke model where administering the ANXA1 mimetic peptide (Ac2-26) decreased the size of the lesion and limited neutrophil infiltration." (PMID 30755225, 2019). "The decisive role of AnxA1 in stroke development and progression has been highlighted in a global murine stroke model mimicking cerebral ischemia caused by atherosclerosis, which is accompanied by cardiac arrest." (PMID 29914106, 2018). "During the last decade, ANXA1 has gained interest as a potential pharmacological tool for the treatment of neurodegenerative disorders, including multiple sclerosis, stroke and Parkinson’s disease." (PMID 27590054, 2016). "There is further pre-clinical evidence for a protective/therapeutic role of ANXA1 in the cerebral vasculature in stroke and other neurovascular diseases." (PMID 27655189, 2016). "Several studies have indicated a role for ANXA1 in neurological diseases, including Alzheimer’s disease (AD), and stroke; although the most compelling evidence is for an involvement in the pathology of MS." (PMID 27655189, 2016).